RNU6-959P (RNA, U6 small nuclear 959, pseudogene)
Gene: Small nuclear RNA gene on chromosome 2 (191,121,950 to 191,122,056, forward strand). Ensembl gene ENSG00000207402.
Homologues: Orthologues: chimpanzee U6 (99% identical), macaque U6 (97% identical), mouse Gm25258 (92% identical), guinea pig U6 (87% identical), pig U6 (81% identical), rabbit U6 (79% identical). Paralogues in human: RNU6-116P (90% identical), RNU6-16P (90% identical), RNU6-17P (90% identical), RNU6-18P (90% identical), RNU6-33P (90% identical), RNU6-480P (90% identical), RNU6-1 (89% identical), RNU6-1060P (89% identical), RNU6-1251P (89% identical), RNU6-12P (89% identical), RNU6-13P (89% identical), RNU6-15P (89% identical), and 1287 more.